SDAD1 (SDA1 domain containing 1)
Description:
Required for 60S pre-ribosomal subunits export to the cytoplasm.
Synonyms: hSDA; FLJ10498; Sda1
Tractability: Small molecule: a structure with a bound ligand is known. PROTAC: ubiquitination databases record sites on it; its protein half-life has been measured.
Gene: Protein-coding gene on chromosome 4 (75,940,950 to 75,990,962, reverse strand). Ensembl gene ENSG00000198301.
Subcellular location: Nucleus, nucleolus
Subcellular location (Human Protein Atlas): Nucleoli; Nucleoplasm
Gene Ontology:
Biological process: ribosomal large subunit biogenesis; ribosomal large subunit export from nucleus
Cellular component: nucleolus
Genetic constraint (gnomAD): Loss-of-function variants: 46 observed, 63.1 expected, observed/expected ratio (o/e) 0.73, 90% interval 0.57 to 0.93. The upper end of that interval is the gene's LOEUF score, 0.93, which puts it in group 3 of 6, group 1 being the genes least tolerant of losing a copy. Missense variants: 550 observed, 603.59 expected, observed/expected ratio (o/e) 0.91, 90% interval 0.85 to 0.98. Synonymous variants: 195 observed, 203.23 expected, observed/expected ratio (o/e) 0.96, 90% interval 0.85 to 1.08.
Homologues: Orthologues: chimpanzee SDAD1 (100% identical), macaque SDAD1 (99% identical), rabbit SDAD1 (95% identical), pig SDAD1 (95% identical), dog SDAD1 (95% identical), mouse Sdad1 (94% identical), rat Sdad1 (92% identical), tropical clawed frog sdad1 (82% identical), zebrafish sdad1 (77% identical), Drosophila melanogaster Mys45A (53% identical), Caenorhabditis elegans pro-3 (41% identical).
Diseases named in the same sentence as SDAD1 in open-access papers:
SDAD1 is named in the same sentence as 13 diseases in open-access papers, as found by Europe PMC text mining. Sharing a sentence is not in itself a finding about the gene and the disease. The quoted sentences say what the papers report.
colon cancer (5 papers, 2017 to 2022). "miR-378 restrains cell aggressive behaviors through inhibiting SDA1 Domain Containing 1 (SDAD1) in colon cancer." (PMID 35692504, 2022). "Knockdown of SDAD1 significantly reduced the proliferation of colon cancer cells, suggesting that SDAD1 promotes proliferation of colon cancer cells." (PMID 28725241, 2017). "We also confirmed that SDAD1 is a direct target gene for miR-378, and that SDAD1 promotes the proliferation, migration and invasion of colon cancer cells." (PMID 28725241, 2017). "miR-378 inhibits the proliferation, migration and invasion of colon cancer cells by targeting SDAD1, defining miR-378 as a potential target for the diagnosis and treatment of colon cancer." (PMID 28725241, 2017). "SDAD1 is a direct target gene of miR-378, and knockdown of SDAD1 suppresses the proliferation, migration and invasion of colon cancer cells." (PMID 28725241, 2017). "The results showed a decreased migration and invasion of colon cancer cells when SDAD1 was knocked down." (PMID 28725241, 2017). "Transwell migration and invasion experiments indicated that SDAD1 promotes colon cancer cell migration and invasion abilities by facilitating EMT." (PMID 28725241, 2017). "By co-transfecting miR-378 with the SDAD1–3’UTR reporter vector into colon cancer cells, we detected the activity of luciferase to demonstrate the condition of miR-378 targeting SDAD1." (PMID 28725241, 2017). "We also investigated the effect of SDAD1 on the migration and invasion of colon cancer cells using Transwell migration and invasion assays." (PMID 28725241, 2017). "For instance, it inhibited colon cancer cell proliferation, migration, and invasion via SDAD1." (PMID 33372356, 2021). "MicroRNA 378 inhibits proliferation and migration of colon cancer cells by targeting SDAD1." (PMID 32423014, 2020). "We next explored whether the effects of SDAD1 on the proliferation and migration of colon cancer cells are consistent with this targeting relationship." (PMID 28725241, 2017). "This is the first identification of an oncogene role for SDAD1 in colon cancer cells." (PMID 28725241, 2017). "SDAD1 promotes the proliferation of colon cancer cells by reducing apoptosis." (PMID 28725241, 2017). "Also, knockdown of SDAD1 in SW480 colon cancer cells can significantly inhibit the cell EMT process." (PMID 28725241, 2017). "The SDAD1 level was higher in the colon cancer tissues than in adjacent normal tissues." (PMID 28725241, 2017). "SDAD1 not only promotes proliferation, migration and invasion but also inhibit apoptosis and promotes EMT of colon cancer cells." (PMID 28725241, 2017).
breast carcinoma (2 papers, 2016 to 2020). "Besides, lncRNA SNHG7 has been found to promote tumorigenesis of breast cancer cells by activating epithelial-mesenchymal transition (EMT) and Notch-1 signaling pathway as well as stabilize SDA1 domain containing 1 (SDAD1) mRNA and induce cardiac hypertrophy." (PMID 32507765, 2020).
cardiac hypertrophy (2 papers, 2020 to 2022). "SNHG7 was up-regulated in the in vitro ANT-treated samples as well as ANT-treated patients, while a study in neonatal rat cardiomyocytes revealed that the up-regulation of the SNHG7 genes can stabilize SDAD1 mRNA, and then facilitate cardiac hypertrophy." (PMID 35415316, 2022).
colorectal cancer (1 paper, 2021). A primary or metastatic malignant neoplasm that affects the colon or rectum. "MiRNA-378 can inhibit the expression of SDAD1 to inhibit the proliferation, migration, and invasion of colorectal cancer cells." (PMID 34712323, 2021).
COVID-19 (1 paper, 2022). A disease caused by infection with severe acute respiratory syndrome coronavirus 2. "CDC25A, GUSB, MYBL2, and SDAD1 were identified as key genes in severe COVID-19." (PMID 35887528, 2022).
cancer (4 papers, 2017 to 2021). A tumor composed of atypical neoplastic, often pleomorphic cells that invade other tissues. "Enforced expression of miR‐378 not only restrained cancer cell proliferation, but also suppressed carcinogenesis by directly targeting SDAD1." (PMID 32061007, 2020). "The expression of SNHG7, as well as SDA1 domain containing 1 (SDAD1), a novel protein determined in human cancers, was raised in AngII-induced neonatal rat cardiac myocytes (NRCMs) hypertrophy." (PMID 31694052, 2019). "SDAD is a gene family which has not been extensively studied, and the role and mechanism of SDAD1 in cancer have not been reported yet." (PMID 28725241, 2017).
SDAD1 also shares sentences with these, for which no sentence is quoted: infection (5 papers); necrotizing fasciitis (3); skin infection (2); tumor (2); gastric cancer (1); renal cell carcinoma (1); skin abscess (1).